CSPG4 (chondroitin sulfate proteoglycan 4)
Diseases named in the same sentence as CSPG4 in open-access papers (continued):
Sharing a sentence is not in itself a finding about the gene and the disease.
tumor (continued). "The targeting of CSPG4 with mAbs in preclinical experiments showed potential anti-tumor activity with no apparent harmful side effects." (PMID 36768830, 2023). "Overall, we demonstrated the cancer target-specific in vitro functions of CSPG4 IgE, and Fc-mediated effector activity restricted to target-expressing tumor cells, but not to low- or non-expressing normal cells." (PMID 37185332, 2023). "CSPG4-specific antibodies, and engineered chimeric antigen receptor (CAR) lymphocyte therapies, have previously been shown to significantly reduce lung metastases and tumor recurrence in mouse models of melanoma." (PMID 37185332, 2023). "Given that it might well be that MHC-restricted anti-CSPG4 TCR are more sensitive in contrast to anti-CSPG4 CAR-T cells, on-target off-tumor toxicity must be critically assessed before any clinical evaluation of this TCRs is initiated." (PMID 37849763, 2023). "As for the “physical barrier,” targets that act on the tumor mesenchyme or microvasculature (FAP, CSPG4, etc.)may also improve the penetration of CAR-T cells in the TME." (PMID 38187386, 2023). "As the authors expected, the CAR-T cells target the human chondroitin sulfate proteoglycan 4 (CSPG4) and aPDL1 antibodies binding to the tumor cells and blocking PDL1, and the combined CAR-T-P-aPDL1@gel system efficiently prevented the tumor recurrence after surgery in mice." (PMID 36276066, 2022). "We analyzed CSPG4 gene expression in 1378 localized STS clinical samples, and searched for correlations with clinicopathological data, including disease-free survival (DFS), and with tumor immune features." (PMID 36221119, 2022). "By contrast, the "CSPG4-high" tumors displayed immune profiles suggesting an immune desert or immune-excluded tumor microenvironment, lacking all kinds of immune cells required to mount an effective anti-tumor response, except for the NKbright cells." (PMID 36221119, 2022). "We show that expression of CSPG4 in STS samples is heterogeneous and associated independently with shorter DFS and with an immune landscape not favorable to anti-tumor cytotoxic response." (PMID 36221119, 2022). "Through the analysis of the semi-serial sections, NG2/CSPG4 immunoreactivity was mutually exclusive from that of GFAP in tumor cells but not in reactive astrocytes." (PMID 32599896, 2020). "Unlike PBS controls, complete tumor growth arrest was observed in four out of seven mice treated with a single dose of anti-CSPG4-(PDD)." (PMID 32331483, 2020). "Survival analysis of the tumor sub-group of 15 GB patients with recorded FUs was not possible because among the three NG2/CSPG4-positive cases, one died after nine months and two were still alive at 12 months." (PMID 32599896, 2020). "We combined positive selection, using CSPG4 and CD146 MACS microbeads and ParsortixTM, in order to prevent the loss of marker-negative tumor cells." (PMID 31671846, 2019). "Nevertheless, on-target/off-tumor toxicity exerted by CSPG4-CAR-T cells against pericytes and other non-malignant tissues stirs serious concerns and poses a major challenge to CSPG4-CAR-T cell therapy." (PMID 31779130, 2019). "Chondroitin sulfate proteoglycan 4 (CSPG4), a transmembrane glycoprotein with functional roles in tumor migration, invasion, angiogenesis, and metastasis, has emerged as a promising tumor antigen target due to its overexpression in several solid cancer types and limited expression in normal tissue." (PMID 30400835, 2018). "Chondroitin sulfate proteoglycan 4 (CSPG4) is overexpressed on differentiated tumor cells and CICs obtained from TNBC patient specimens, suggesting that CSPG4 may be a clinically relevant target for the imaging and therapy of TNBC." (PMID 29561763, 2018). "In VCaP xenografts few Cspg4 (Ng2) positive cells were found around the tumor but not within the tumor." (PMID 29988965, 2018).
tumor (continued). "Gene expression profiling indicated substantial down-regulation of insulin-like growth factor binding protein (Igfbp) genes when Ng2/Cspg4 is depleted at tumor initiation, but not when Ng2/Cspg4 is depleted after tumor initiation." (PMID 29196603, 2018). "GBM neurosphere engraftment in nude mice followed by the infusion of a third generation CSPG4-CAR T-cell demonstrated lasting efficacy and minimal antigen escape, at least partially due to the upregulation of CSPG4 on tumor cells by microglia-derived TNF-α in the tumor microenvironment." (PMID 30740109, 2018). "Immunotherapy approaches using CAR-Ts could be an effective treatment modality in GB that overcomes tumor escape and NG2/CSPG4 intratumor heterogeneity." (PMID 30213051, 2018). "Nevertheless, the authors did not investigate the specific implications of CSPG4 expression in the tumor formation process." (PMID 29375561, 2017). "Furthermore, fluorescence immunohistochemistry experiments confirmed that our constructs can distinguish between healthy and TNBC tumor tissues, because the latter express high levels of EGFR, EpCAM or CSPG4." (PMID 27448975, 2016). "As a proxy for the quantity of original patient stroma in each PDX sample, human expression levels of two CAF markers that are rarely expressed by tumor epithelial cells, fibroblast activation protein alpha (FAP) and chondroitin sulfate proteoglycan 4 (CSPG4), were assessed." (PMID 26980748, 2016). "The following concentrations of detergents did not influence cell growth of neither PBMC nor CSPG4 positive tumor cells positively or negatively: Tween® 20 (0.0067%, 0.0013%), Tween® 80 (0.0067%, 0.0013%), saponin (0.0067%), and Na-deoxycholate (0.0013%)." (PMID 26469402, 2015). "The authors also discovered that while tumor-specific IgG1 antibodies, directed against the chondroitin sulfate proteoglycan 4 (CSPG4) tumor antigen, were able to facilitate monocyte-mediated ADCC and ADCP of tumor cells, tumor-specific IgG4 was unable to elicit the same response." (PMID 26497518, 2015). "The viability of the CSPG4 negative tumor cells was not affected by the addition of r28M at any time." (PMID 26469402, 2015). "In tumour vessels, NG2/CSPG4 fragments co-localized with Coll IV at the VBM/pericyte interface, forming clearcut rims denoted as 'pericyte lacunae', restricted specific domains pertaining to shed fragments and never seen to be co-localized with pericyte-specific isoforms identified by mAb 2161F9." (PMID 24386429, 2013). "The reactivity pattern initially observed on reference tumour cell lines indicated that the mAbs recognized 48 immunologically distinct NG2/CSPG4 isoforms, and a total of 14 mAbs was found to identify NG2/CSPG4 isoforms in foetal and neoplastic cerebral sections." (PMID 24386429, 2013). "The characterization of CSPG4 interaction with NEDD9 may provide insights for understanding mechanisms of growth and survival of these tumor stem cells." (PMID 22984505, 2012). "In addition, CSPG4 and CHST11 were over-expressed in tumor-containing clinical tissue specimens compared with normal tissues." (PMID 21658254, 2011). "The data further suggest that overexpression of both CSPG4 and CHST11 genes in tumor cells may contribute to a superior metastatic potential." (PMID 21658254, 2011). "However, challenges remain, as CSPG4-negative tumor cells persist, necessitating combinational strategies." (PMID 41029427, 2025). "However, considering that CSPG4 CAR T cells were not able to achieve complete tumor eradication, we sought to evaluate the efficacy of CAR T cells targeting a different tumor antigen." (PMID 40847369, 2025). "Importantly and counterintuitively, strong CSPG4 expression in nevi does not indicate malignancy, particularly when other tumor markers are absent." (PMID 40700516, 2025).
tumor (continued). "This study demonstrated that DNA vaccines could potentially be an effective alternative to anti-idiotypic antibody vaccination, although the mechanism by which such a therapy could target CSPG4-negative tumours requires further investigation." (PMID 39409881, 2024). "In addition, CSPG4 affects EMT-related pathways by influencing extracellular matrix receptor interactions, extracellular matrix disassembly, and extracellular matrix assembly, thereby affecting tumor progression." (PMID 38015710, 2023). "Although previous findings of CSPG4 IgE administration in a fully immunocompetent rat model may indicate lack of on-target off-tumor toxicity against minimally CSPG4-expressing normal tissues, the safety of CSPG4 IgE requires further investigation." (PMID 37185332, 2023). "Therefore, in in vivo mouse models presented herein, CSPG4 IgE selectively targets human CSPG4-expressing tumors and not any off-tumor endogenous mouse CSPG4 antigen." (PMID 37185332, 2023). "In this line, “CSPG4-high” GIST, as compared to “CSPG4-low” GIST, might be more sensitive to CSPG4-CAR.CIKs, not only because of higher target expression level, but also thanks to a more favorable anti-tumor cytokine microenvironment with a synergic action of resident cytotoxic T and NK cells." (PMID 35267618, 2022). "Patients with “CSPG4-high” STS, theoretically candidate for CAR.CIKs, display shorter DFS and an immune environment unfavorable to vulnerability to CAR.CIKs, which could be improved by combining anti-angiogenic drugs able to normalize the tumor vasculature." (PMID 36221119, 2022). "Using this approach, the elimination of antigen-negative solid tumor cells could be shown in vitro and in vivo rendering CSPG4-specific TRUCKs attractive for engaging tumor cells remaining CSPG4-negative after decitabine treatment." (PMID 36291817, 2022). "Hence, the concept of targeting decitabine-upregulated CSPG4 has to be placed into a broader context encompassing strategies to simultaneously engage CSPG4-negative tumor cells." (PMID 36291817, 2022). "We report that despite the fast clearance of IgE from the blood, the tumor-to-blood ratios of anti-CSPG4 IgE were much higher than those of a non-tumor targeted IgE, suggesting that anti-CSPG4 IgE could reach its target antigen in tumors." (PMID 34513315, 2021). "No anti-tumor effect was observed in A2058 cells treated with up to 250 μg/ml α-CSPG4 rIgE." (PMID 31769737, 2020). "We have recently shown that by using a combined a marker‐dependent (CSPG4 and CD146MACS microbeads) and marker‐independent (Parsortix, Angle plc) detection method, 32% of patients were CTC‐positive with an increase in CTC‐positivity with increased tumor staging." (PMID 32246814, 2020). "Finally, to investigate whether developed tumors in mice could still respond to anti-CSPG4-(PDD), developed tumors from the three mice were harvested alongside a tumor from an isotype-(PDD)-treated mouse." (PMID 32331483, 2020). "Consequently, CSPG4-CAR-T cells could mount a multi-hit attack against GBM cells, simultaneously engaging bulk tumor cells, tumor stem cells and tumor blood vessels." (PMID 31779130, 2019). "In order to determine whether the lentivirally transduced T cells can be additionally transfected with mRNA coding for a tumor-specific CAR, the surface expression of the gp100-specific TCR and the CSPG4-specific CAR were examined following RNA electroporation." (PMID 31137488, 2019). "Thus, the TNF-inducible expression of CSPG4 in combination with TNF elaborated from CSPG4-CAR-T cells may create a feed-forward loop culminating in uniform CSPG4 expression on GBM cells, paving the way for complete tumor eradication." (PMID 31779130, 2019). "Therefore, concerted upregulation of CSPG4 and CHST11 may induce expression of a unique molecular entity that may increase the metastatic capabilities of tumor cells." (PMID 21658254, 2011).
tumor (continued). "Importantly, non-malignant cells, both in the tumor microenvironment and across broader cell types, generally presented low CSPG4 transcript counts, with notable exceptions being Sertoli cells, oligodendrocyte precursors cells, and a population of smooth muscle cells." (PMID 40082557, 2025). "Therefore, using CSPG4 as a CAR-T target in solid tumors is attractive because doing so may give CAR-T cells the ability to attack primary and metastatic tumor cells and the tumor-supportive stroma." (PMID 36768830, 2023). "However, the targetability of decitabine-induced CSPG4 on tumor cells has never been shown so far." (PMID 36291817, 2022). "Hence, based on the overlapped upstream miRNAs and correlation analysis, we confirmed that the three key miRNAs (hsa-miR-124-3p, hsa-miR-26b-5p, and hsa-miR-192-5p) could regulate the four hub genes (CAV1, COL6A2, CSPG4, and PCOLCE) in GEM-resistance and tumor immune microenvironment." (PMID 35127724, 2021). "Hence, deploying CSPG4-CAR-T cells as monotherapy bears risks of sparing CSPG4-negative tumor cells, which could provide the basis for refractory disease or relapse." (PMID 31779130, 2019). "Furthermore, our data also illustrate the complexity in interpreting results from genetically engineered mice, as the data from deletion of Ng2/Cspg4 at tumor initiation probably do not necessarily pertain to the more clinically relevant experiment of Ng2/Cspg4 inhibition in established tumors." (PMID 29196603, 2018). "Monoclonal antibodies recognizing CSPG4 could be conjugated to a radioactive isotope for radioimmunotherapy, designed to target radiation directly and more specifically to tumor cells, with the aim of reducing non-specific exposure of normal cells to the radioactive isotope." (PMID 29375561, 2017). "Furthermore, the application of some fractions led to enhanced growth of CSPG4 positive and negative cells, but CSPG4 negative tumor cells could not be killed with any of the fractions at any concentration." (PMID 26469402, 2015). "The functionality of multiple different CARs, with the widespread expression of CSPG4 on multiple malignancies, suggests that CSPG4 may be an attractive candidate tumor antigen for CAR-based immunotherapies using appropriate technology to limit possible off-tumor toxicity." (PMID 25197555, 2014). "One, 4, or 7 days after CSPG4‐CAR‐T‐cell infusion, brains were harvested, bisected along the interhemispheric fissure, and separated into “tumor” and “contralateral” (nontumor) hemispheres." (PMID 38023712, 2023). "Taken as a whole, what this work has also demonstrated is that assessment of CSPG4 as a tumour marker or therapeutic target in SCC should not be conducted independently of stage, and the tumour environment." (PMID 36428658, 2022). "CSPG4 CAR-T cells resisted brain tumor growth in cultured neurosphere and glioma xenograft mice models without signs of tumor escape." (PMID 36261831, 2022). "As anticipated, treatment of the xenograft mice at the same dose level with the equivalent non-binding isotype-(PDD) control ADC, the unconjugated anti-CSPG4-IgG1 antibody plus free payload, PDD alone or PBS vehicle control did not impair tumor growth." (PMID 32331483, 2020). "Finally, it is thus not surprising that CSPG4 is overexpressed on CIC and tumor-derived exosomes that are emerging as major players in cancer development and progression, contributing to recurrences, metastasis formation and chemoresistance." (PMID 28668095, 2017).
cancer (108 papers, 2006 to 2026). A tumor composed of atypical neoplastic, often pleomorphic cells that invade other tissues. "The results of our analysis, visualized as a ridge plot, revealed a significant association between CSPG4 and “cancer immunotherapy by PD1 blockade” in the BLCA immune microenvironment." (PMID 38015710, 2023). "This is in line with the reported role of CSPG4 in several cancer-associated pathways, including angiogenesis, dissemination, metastasis, proliferation and survival." (PMID 37901209, 2023). "CSPG4-CAR-T cells concomitantly targeted CSPG4+ TNBC cells and cancer-associated fibroblasts (CAFs), and CSPG4 was detected in TNBC stem cells." (PMID 37457288, 2023). "CSPG4 has been shown to be directly involved in aggressive tumor behavior in several cancer histotypes, as it is also overexpressed on cancer stem cells and is associated with poor prognosis." (PMID 36556464, 2022). "Being a cell-surface tumor antigen, CSPG4 represents an ideal target for effective anti-cancer immunotherapy as CSPG4+ cancer cells are potentially susceptible to the concomitant attack of vaccine-inducible T cells and antibodies." (PMID 35224082, 2022). "The region on BTA 21 has been associated with somatic cell score in Norwegian Red cattle and contains the CSPG4 gene, which is also linked to cancer in humans." (PMID 32582285, 2020). "Binding of CSPG4 to collagen VI has also been implicated in relaying survival signals to cancer cells by virtue of PI3K activity." (PMID 31779130, 2019). "In sum, CSPG4-expressing cancer-associated stromal cells represent an important source for growth and proliferation stimuli." (PMID 31779130, 2019). "CSPG4 is strongly associated with several hallmarks of advanced cancer, including proliferation, invasion and metastasis." (PMID 28657611, 2017). "CSPG4 is implicated in several signaling pathways believed to drive cancer progression, particularly proliferation, motility and metastatic spread." (PMID 28657611, 2017). "The association of CSPG4 with typically treatment-resistant cancers and its putative overexpression in CSCs qualify it as an ideal target for immunotherapy." (PMID 28657611, 2017). "Upregulation of CSPG4 in malignant tumors is putatively linked to their ability to bypass inherent regulatory mechanisms by suppressing apoptotic signaling, proliferating at an elevated rate and acquiring anchorage independence." (PMID 28657611, 2017). "The published records predicted the overexpression and pathogenic relevance of CSPG4 in pancreatic malignancies in line with pro-stromal, pro-angiogenic and pro-malignant activities in other cancers." (PMID 24932730, 2014). "As a protein associated with several human cancers and one that is also targeted by a toxin produced by a prominent human pathogen, therapies that reduce CSPG4 expression could be highly beneficial in treating multiple diseases." (PMID 36972308, 2023). "Cancer-associated antigen targets, such as chondroitin sulfate proteoglycan 4 (CSPG4), may be promising for cancer treatment." (PMID 37185332, 2023). "CSPG4 is a cancer-associated protein and a receptor for C. difficile TcdB." (PMID 36972308, 2023). "Provided that OSA is associated with the increased risk of cancer development, the elevated protein levels of CSPG4 could be linked to the cancer development in the OSA patients." (PMID 35480887, 2022). "These may provide opportunities for therapeutic interventions targeting CSPG4 and multiple cancer-associated pathways this molecule may be involved in." (PMID 29375561, 2017). "Notably, angiogenic NG2/CSPG4 isoforms of foetal brain appeared overall to be more glycosylated than their cancer-associated isoform counterparts." (PMID 24386429, 2013). "Using a combination of literature searching and reanalysis of published data this review has sought to illuminate the dynamic and multivariate roles that CSPG4 might play in cancer progression, and to assess CSPG4 expression as a diagnostic marker in aggressive SCCs." (PMID 36428658, 2022).